CXCR2 (C-X-C motif chemokine receptor 2)
Diseases named in the same sentence as CXCR2 in open-access papers (continued):
Sharing a sentence is not in itself a finding about the gene and the disease.
tumor (continued). "However, both the mechanisms by which neutrophils play a tumor-promoting role in humans and the mechanisms by which CXCR2 inhibition might have a tumor-suppressive effect in human cancer are not completely understood." (PMID 38898176, 2024). "Given the immunosuppressive role of CXCR2-recruited MDSC in the tumor microenvironment, CXCR2 antagonists like navarixin might complement the action of programmed cell death protein 1 (PD-1) or programmed cell death ligand 1 (PD-L1) inhibitors in tumor types with low response rates to these agents." (PMID 38324085, 2024). "The increased exposure of neoantigens and expression of chemokines in tumor cells induced by radiotherapy may offer new avenues for CAR-NK therapy development, such as CARs targeting NKG2DL or overexpressing chemokine receptors (CXCR1, CXCR2, and CXCR4) through CAR design." (PMID 38162672, 2023). "The AFP level, liver function, and TNM stage in the CXCR2+ low group were significantly different from those in the CXCR2+ high group, while other clinicopathological features such as age, gender, tumor number, tumor diameter, and HBsAg were not significantly different." (PMID 37403022, 2023). "To date, increasing evidence has demonstrated that the expression levels of CXCL1 and CXCR2 are frequently upregulated in several human cancers, and CXCL1 may serve as a source of autocrine/paracrine signal for the malignant process in the tumor microenvironment." (PMID 35764974, 2022). "However, CXCR2 is not expressed in T cells, and modifying T cells to express CXCR2 is beneficial in directing T cell migration towards cancer and infiltrating the cancer mass to enhance the anti-tumor response." (PMID 35269786, 2022). "Taken together, these results indicated that targeting CXCR2 can promote tumor growth in vivo but had little or no direct effect on the proliferation of CRC tumor cells in vitro, which may be attributed to the difference between extracellular factors and intracellular factors in the tumor process." (PMID 34025668, 2021). "Interestingly, PMN-MDSC frequencies in the BM and peripheral blood were not significantly altered upon the therapy, indicating that anti-CXCR2 therapy could inhibit PMN-MDSC migration to the tumor without affecting their amounts at the systemic level." (PMID 33578808, 2021). "The non-functional condition of CXCR2 is known to result in lack of neutrophil recruitment or activation in inflammatory diseases, which can also be a possible explanation of suppressed tumor growth of Cl66 cells in Cxcr2−/− mice in comparison with the wild type mice." (PMID 30871004, 2019). "However, blockade of CXCR2 largely but not completely inhibited tumor growth, suggesting that Snail might activate other factors involved in anti-tumor immunity, and the issue requires further investigation." (PMID 29703902, 2018). "Moreover, this study found that PADI4 may contribute to cancer development and progression by increasing the expression of CXCR2, KRT14 and TNF-α, which activate pro-inflammatory processes, angiogenesis, cell migration, cell proliferation and cell differentiation in tumor tissues." (PMID 27556695, 2016). "As the binding receptors CXCR1 and CXCR2 are expressed on myeloid derived cells and carcinoma cells, CXCL1 expression in CAFs may serve to regulate paracrine signaling interactions with immune cells and cancer cells to promote chemo-resistance and tumor progression." (PMID 25344051, 2014). "Therefore, reduced levels of IL-6 in response to neutrophil depletion, CXCR2 inhibition, or lack of NE could be considered as another mechanism of tumor regression." (PMID 24321240, 2013). "It has been reported that depression promotes tumor growth and metastasis by affecting TAM/CXCL1 in the tumor microenvironment, but the downstream receptors of CXCL1 (such as CXCR1/CXCR2) have not been investigated in these studies." (PMID 40839237, 2025).
tumor (continued). "Last, we observed a greater number of tumor-infiltrating L2-8R-70 CAR T cells (CD8+CXCR2+, defined by mouse CD8 and human CXCR2 markers) compared with 8R-70 CAR T cells and the no–CAR T control cells." (PMID 40591413, 2025). "We demonstrate that combining SB225002 (a potent, selective and non-peptide CXCR2 antagonist) with PD1 blockade and partial irradiation (LDRT + HDRT) further improves tumor control and mouse survival." (PMID 39397001, 2024). "In conclusion, our study provides evidence that co-expression of CXCR2 in CAR-T cells can enhance antitumor effects, increase T-cell recruitment and proliferation at PDAC tumor sites, and does not produce cellular toxicity." (PMID 38430267, 2024). "CXCR1 expression, not CXCR2, was shown to upregulate the tumor suppressor ITM2A to diminish cell proliferation and inhibit tumor growth." (PMID 39766038, 2024). "While MOC1 tumor cells did not express high levels of CXCR1/2, we did observe a population of CXCR2+CD11b+Ly6G+ myeloid cells in the spleens and tumors of these mice which have been shown to be highly immune suppressive." (PMID 39639338, 2024). "CXCR2 is also a mediator of MDSC recruitment in regional lymph nodes, playing a role in preventing tumor metastasis, and CXCR‐antagonist SB225002 reversed MDSC trafficking." (PMID 37547175, 2023). "Currently, several small-molecule inhibitors of CXCR2, including “AZD5069”, are being investigated for their anticancer effects in preclinical and clinical studies in several tumor types but not yet investigated in TNBC." (PMID 35517812, 2022). "Although it was found that CXCR2 expression had no influence on the cytotoxicity of CAR‐T cells in vitro, CXCR2 CAR‐T cells did enhance the infiltration and expansion in the tumour site in vivo with improved trafficking and anti‐tumour responses." (PMID 36495108, 2022). "The absence of IFN-β augmented intratumoral infiltration of CXCR2-expressing neutrophils, which abundantly produced VEGF and MMP-9 and as a consequence, neutrophil depletion reduced tumor angiogenesis." (PMID 32422991, 2020). "The results showed that the phosphorylation of ERK1/2 and STAT3 was up-regulated, whereas a lack of CXCR2 suppressed the activation of ERK1/2 and STAT3 in the tumor conditions." (PMID 31395859, 2019). "In contrast, a significantly stronger T-cell presence was observed in the tumors of two mice treated with A20-28z CXCR2 CAR T-cells (the third mouse had no macroscopically evident tumor at the experimental endpoint), including infiltration into the tumor core." (PMID 31091832, 2019). "Also, combination therapies may enhance tumor cell immunogenicity while reducing the efficacy of immunosuppressive molecules such as indoleamine 2,3-dioxygenase (IDO), C-X-C Motif chemokine receptor 2 (CXCR2), lymphocyte-activation gene 3 (LAG-3), phosphoinositide 3-kinase (P13K), for example." (PMID 31014381, 2019). "The majority of tumor-infiltrating mast cells expressed CXCR4 but not CCR2, CCR4, CCR5, CCR7, CXCR1, CXCR2 or CXCR7, while, mast cells in peritumoral or non-tumor tissues showed lower CXCR4 expression." (PMID 30808413, 2019). "Using specific inhibitors, we demonstrated that each of these cytokines, particularly IL‐6 and GRO‐α, modulates the invasive behaviour of tumour cells, whereas the mechanism of transendothelial migration is completely independent of GRO‐α/CXCR2 signalling." (PMID 29517849, 2018). "The results of the cell growth and foci formation assays revealed that the overexpression of CXCL5 and/or CXCR2 did not influence NPC cell growth, tumour formation or cell proliferation." (PMID 29665837, 2018). "For all assessed RCC tumor supernatants, the CXCL1 but not CXCL8 concentration correlated significantly (p = 0.014) with the migration of CXCR2-transduced NK cells relative to NGFR-transduced NK cells." (PMID 28923105, 2017). "In Cxcr2 knockout mice, lack of the CXCL8–CXCR2 axis in the tumor microenvironment prevented CRC growth and metastasis." (PMID 27136535, 2016).
tumor (continued). "After intraperitoneally implanting CXCR2-negative (SKA) and positive (SKCXCR2) cells, we compared the extent degree of tumor burden." (PMID 27723802, 2016). "It is surprising that inhibition of CXCL1, which is also a CXCR2 agonist similar to CXCL2, exerted no inhibitory effects on the tumor suppression and neutrophil infiltration induced by HVJ-E+poly I:C treatment." (PMID 27259252, 2016). "Similar to mLy-6G Ab treatment, neutrophils in BALF of NTHi-exposed mice were not affected by the CXCR2 inhibitor, but it reduced the number of infiltrating neutrophils with MDSC/progenitor cell characteristics in the lung parenchyma and tumor sites." (PMID 24321240, 2013). "Since ASPC-1 and BxPC-3 cells do not express CXCR1 and CXCR2, our data favors a paracrine role for IL-8 in PDAC possibly through the stimulation of endothelial cell proliferation and/or mobilization to remodel tumor vasculature." (PMID 22815748, 2012). "Comparison of the mean IRS scores for CXCR1, CXCR2 and CXCL1 in malignant and non-malignant tissue confirmed higher expression of each chemokine marker in the tumour epithelium relative to adjacent normal colorectal tissue." (PMID 21285972, 2011). "Whatwe document is that IL-8 mediates the retention inside the tumor microenvironment.This is not a surprise since IL-8 receptors, CXCR1 and CXCR2, are expressed on DCand are functional in classical chemotaxis assays." (PMID 21423807, 2011). "It is of great interest that the overexpression of CXCR1 or CXCR2 in SBC-2, a non-tumourigenic cell line induced tumour formation." (PMID 19401689, 2009). "In vitro, WT, but not Cxcr2-/-, neutrophils enhanced CD8+ T cell activation, partly via ICAM-1, and directly induced tumor cell death, supporting their anti-tumor function." (PMID 41977328, 2026). "To exclude the confounding effects induced by primary tumor, we constructed lung or liver experimental metastasis models by injecting 4T1 cells via tail vein or EO771 cells intrasplenically and applied Dox with or without CXCR2 or CFB inhibition." (PMID 41480760, 2026). "MIF exerts its function of promoting leukocyte recruitment to inflammatory sites by noncognate interaction with the chemokine receptors CXCR2 and CXCR4, and regulates the MIF-stimulated survival of macrophages, B cells, and tumor cells through its receptor cluster of differentiation 74 (CD74)." (PMID 39851524, 2025). "However, we do not observe the obviously differences of CXCR2 expression between PMN-MDSCs and M-MDSCs from lung of 4T1 tumor-bearing mouse." (PMID 37268941, 2023). "Results showed tumor cells usually have negative CXCR1 and CXCR2 staining." (PMID 37765018, 2023). "Although CXCR2 was reported to be expressed also on the vascular endothelium, contributing to tumor angiogenesis, we failed to observe any changes in the frequency of CD31+ tumor infiltrating endothelial cells upon CXCR2 inhibition." (PMID 33578808, 2021). "Many strategies such as expressing chemokine receptors CXCR2/CCR2b, CXCR3 and use of oncolytic virus to secrete chemokines RANTES, IL-15 to drive CART cells to tumor sites are being actively tested to drive CART cells to tumor sites in non-GBM tumors." (PMID 33281826, 2020). "While patterns of CXCR2 in immune cells were not consistent with the patterns of immune cells induced by CXCL5, CXCR3 was highly expressed in T cells in the tumour microenvironment of PAAD tissue, which was in agreement with the induced patterns change of immune cells induced by CXCL9/10." (PMID 31913856, 2020). "Unlike CXCR2, poor recognition of PDAC cells by NK cells was not due to systemic immune suppression in the patients, since those isolated from HD also failed to kill the tumor cells." (PMID 31024520, 2019). "Using BMT, we show that CXCR1‐mediated tumor cell–endothelial interactions are not sufficient for NRAS‐driven lung metastasis, which also requires the concurrent involvement of myeloid cells that express CXCR2." (PMID 28341702, 2017).
tumor (continued). "Furthermore, the IL-8/CXCR1/CXCR2 signaling was crucial for the maintenance of stemness features and tumor-initiating ability of TC cells, whereas CXCL1/CXCR2 was not." (PMID 28415590, 2017). "Unlike the xenograft models, CXCR2 was predominantly expressed in CD45+ immune cells with minimal to no expression observed in CK positive MOC1 tumor cells, allowing us to evaluate the effect of SX-682 plus docetaxel on the immune compartment with no direct effect on the tumor cells." (PMID 39639338, 2024). "Similarly the ectopic expression of CXCR1, which is not normally expressed on T cells, or CXCR2, on anti-CD70 CAR T cells, enhanced the trafficking to tumours and elicited tumour regression and improved survival in models of glioblastoma, pancreatic cancer, and ovarian cancer." (PMID 35205725, 2022). "Antagonism of CXCR2 could effectively prevent functional CD8+ T cells and DCs activation from infiltrating tumor sites in a CRC mouse model, which could change the CRC mouse’s antitumor immunity model to promote tumor progression rather than regression." (PMID 34025668, 2021). "Importantly, studies by Steele and colleagues have demonstrated that CXCR2 deletion abrogated tumor metastasis in KPC Cxcr2−/− mice, yet, no benefits were noted in the overall or tumor-free survival between KPC Cxcr2−/− and KPC mice with or without gemcitabine treatment." (PMID 31652904, 2019). "The expression of both CXCL5 and CXCR2 was higher in the NPC primary tissues than in the non-tumour tissues at the protein level as quantified by IHC, and the expression of CXCL5 was primarily localized to the tumour cells rather than the mesenchymal portion of the cancerous tissue." (PMID 29665837, 2018). "Additionally, studies have shown that neutrophil recruitment plays a significant role in liver metastasis rather than the primary tumour in pancreatic cancer, and similar findings have been observed in colon cancer and HCC, highlighting the context-dependent nature of CXCR2’s role." (PMID 39199570, 2024). "The up-regulation of CXCR2 and CXCR1 receptors by HCT116 cells, which do not activate NF-κB in response to CPT, raises the possibility that subgroups of cells in a heterogeneous tumor mass may, under chemotherapy, secrete or respond to soluble factors in the microenvironment." (PMID 25134433, 2014).
cancer (435 papers, 2002 to 2026). A tumor composed of atypical neoplastic, often pleomorphic cells that invade other tissues. "Cxcr2 is a chemokine receptor involved in immune cell trafficking, inflammation, and wound healing that has been implicated in multiple diseases and cancers." (PMID 41609865, 2026). "Cytokines like G-CSF, IL-1β, Interleukin-8, and CXCR1 and CXCR2 agonists have been demonstrated to stimulate cancer-associated NETosis." (PMID 38474175, 2024). "CXCR2 plays an important role in human health and is linked to disorders such as autoimmune disorders, inflammation, and cancer." (PMID 38625857, 2024). "CXCR-2 ligands include CXCL-1, CXCL-2, CXCL-3, CXCL-5, IL-6, CXCL-7 and IL-8, and overall CXCLs/CXCR-2 pathway is implicated in cancer and inflammation." (PMID 38672477, 2024). "It has been proved that blocking the biological axis of CXC chemokine/CXCR2 can reduce the risk of malignant tumors." (PMID 37576896, 2023). "CXCL1 increases the proliferation of OSCC cancer cells, which is associated with the activation of CXCR2 that transactivates epidermal growth factor receptor (EGFR)." (PMID 37408240, 2023). "When adjusted for endometrial thickness above 5 mm, GA heterozygotes in the CXCR2 polymorphism were associated with about double the risk of cancer in the overdominant model (OR 2.23 95% CI 1.03–4.83, p = 0.038)." (PMID 38001676, 2023). "In the case of CKS, a lower risk of cancer was found in T-G haplotype carriers for the CXCR2 rs1126579-rs1126580 polymorphisms." (PMID 38001676, 2023). "In the context of cancer, CXCR2 has been implicated in the tumorigenesis of skin and colon cancer, and more recently, has been implicated in tumor metastasis." (PMID 38062888, 2023). "The GA heterozygotes in the CXCR2 SNP were associated with approximately threefold higher cancer risk (p ≤ 0.001)." (PMID 38001676, 2023). "It has been reported that in triple-negative breast cancer, the expression of CXCR2 is associated with higher immune infiltration and more favorable outcomes, whereas CXCR2 ligands have been reported to have cancer-promoting effects." (PMID 35377900, 2022). "CXCR2 is the main receptor for ELR+CXC chemokines to mediate tumorigenesis and development 37, and high expression of CXCR2 is associated with poor prognosis in cancers." (PMID 35280694, 2022). "As such, the CXCR2 blockade requires better understanding of the mechanisms underlying this chemokine axis in cancer biology." (PMID 34575965, 2021). "Studies published so far have associated CXCR2 expression in cancer cells to the epithelial-mesenchymal transition (EMT) phenotype." (PMID 34038868, 2021). "Expression, prognostic significance, and genetic mutations of CXCR2 were analyzed in diverse cancer types based on TCGA and GTEx datasets." (PMID 34840630, 2021). "Oral pretreatment with probiotic Bifidobacterium alleviates intestinal inflammation and colitis-associated cancer through CXCR2 signaling." (PMID 35011369, 2021). "Through the GEPIA2 tool, we investigated the associations of CXCR2 with OS across diverse cancer types." (PMID 34840630, 2021). "In a variety of cancers, it has been shown that CXCR2 was expressed in cancer cells and frequently associated with a poor prognosis." (PMID 32727083, 2020). "Although CXCR2 is expressed highly by circulating neutrophils in relevant models of comparison, such as cancer, it is primarily and functionally associated with upregulation on PMN-MDSCs." (PMID 30081463, 2018). "It was identified that CXCR2 was a risk factor for cancer both in synthetic analysis and subgroup analysis." (PMID 29599927, 2018). "Clear evidence has shown that CXCR2 and its associated ligands play important roles in various types of cancer." (PMID 30246456, 2018). "Our results were the first to suggest that CXCR2 overexpression was associated with poor survival of patients with most cancer types." (PMID 29312644, 2017).